EIF2B3 (eukaryotic translation initiation factor 2B subunit gamma)
Description:
Acts as a component of the translation initiation factor 2B (eIF2B) complex, which catalyzes the exchange of GDP for GTP on the eukaryotic initiation factor 2 (eIF2) complex gamma subunit. Its guanine nucleotide exchange factor activity is repressed when bound to eIF2 complex phosphorylated on the alpha subunit, thereby limiting the amount of methionyl-initiator methionine tRNA available to the ribosome and consequently global translation is repressed.
Synonyms: EIF2Bgamma; EIF-2B; VWM3
Tractability: Small molecule: a structure with a bound ligand is known. PROTAC: ubiquitination databases record sites on it; its protein half-life has been measured.
Gene: Protein-coding gene on chromosome 1 (44,850,522 to 44,986,722, reverse strand). Ensembl gene ENSG00000070785.
Subcellular location: Cytoplasm, cytosol
Subcellular location (Human Protein Atlas): Cytosol; Vesicles
Pathways (Reactome):
Metabolism of proteins: Recycling of eIF2:GDP
Gene Ontology:
Molecular function: guanyl-nucleotide exchange factor activity; protein binding; translation factor activity, RNA binding; translation initiation factor activity
Biological process: cytoplasmic translational initiation; oligodendrocyte development; positive regulation of translational initiation; T cell receptor signaling pathway; translational initiation; response to glucose; response to heat; response to peptide hormone; central nervous system development; translation
Cellular component: cytoplasm; cytosol; eukaryotic translation initiation factor 2B complex
Genetic constraint (gnomAD): Loss-of-function variants: 20 observed, 55.71 expected, observed/expected ratio (o/e) 0.36, 90% interval 0.25 to 0.52. The synonymous counts are far from expectation, so gnomAD's model fits this gene poorly and the ratio says little. Missense variants: 448 observed, 575.52 expected, observed/expected ratio (o/e) 0.78, 90% interval 0.72 to 0.84. Synonymous variants: 153 observed, 199.4 expected, observed/expected ratio (o/e) 0.77, 90% interval 0.67 to 0.88.
Gene-disease validity (ClinGen):
ClinGen rates the evidence that EIF2B3 causes each of these diseases.
leukoencephalopathy with vanishing white matter 3 (autosomal recessive): Definitive.
Homologues: Orthologues: chimpanzee EIF2B3 (99% identical), macaque EIF2B3 (96% identical), rabbit EIF2B3 (94% identical), guinea pig EIF2B3 (92% identical), mouse Eif2b3 (92% identical), dog EIF2B3 (91% identical), rat Eif2b3 (90% identical), pig EIF2B3 (77% identical), tropical clawed frog eif2b3 (64% identical), zebrafish eif2b3 (64% identical), Drosophila melanogaster eIF2Bgamma (35% identical), Caenorhabditis elegans eif-2Bgamma (27% identical). Paralogues in human: EIF2B5 (17% identical), GMPPA (16% identical), GMPPB (16% identical).
Diseases named in the same sentence as EIF2B3 in open-access papers:
EIF2B3 is named in the same sentence as 12 diseases in open-access papers, as found by Europe PMC text mining. Sharing a sentence is not in itself a finding about the gene and the disease. The quoted sentences say what the papers report.
leukodystrophy (3 papers, 2018 to 2024). Leukodystrophies are a group of rare, progressive, metabolic, genetic diseases that affect the brain, spinal cord and often the peripheral nerves. "For example, the protein-coding gene EIF2B3 is required for myelin formation in the early stages of CNS development and is associated with leukodystrophy with vanishing WM." (PMID 39273172, 2024). "The protein encoded by eukaryotic translation initiation factor 2B, subunit gamma (EIF2B3), is a subunit of the initiation factor eIF2B, which is associated with vanishing white matter (VWM) disease and leukodystrophy." (PMID 33109206, 2020).
Leukoencephalopathy (3 papers, 2018 to 2023). This term describes abnormality of the white matter of the cerebrum resulting from damage to the myelin sheaths of nerve cells. "Variants in EIF2B3 cause a recessively inherited leukoencephalopathy with vanishing white matter (OMIM #620313)." (PMID 38031187, 2023). "The mutated gene was EIF2B3, which has been identified in some patients with leukoencephalopathy with vanishing white matter, an autosomal recessive disorder." (PMID 31475473, 2019).
diabetes (1 paper, 2015). "4EBP1 was also positively associated with genes coupled to diabetes pathways, genes regulated by the transcription factors E2F, USF and SP1, the oncogenes HRAS and HOXB13 and several genes involved in negative regulation of translational initiation (EIF4EBP2, EIF2B3, EIF2C2)." (PMID 26698305, 2015).
glioma (1 paper, 2019). A benign or malignant brain and spinal cord tumor that arises from glial cells (astrocytes, oligodendrocytes, ependymal cells). "On the contrary, the EIF2B3 subunit is down-regulated in gliomas including in GBM, but only in the classical subtype." (PMID 31795417, 2019). "In our analysis of gene expression, all EIF2B subunits except EIF2B3 (encoding the γ subunit) are overexpressed in gliomas compared to non-tumoral brain tissue." (PMID 31795417, 2019).
neurological disease (2 papers, 2021). "VWM is a neurological disease caused by mutations in the eukaryotic translation initiation factor 2B (EIF2B) that produce bi-allelic pathogenic variants in one of five genes: EIF2B1, EIF2B2, EIF2B3, EIF2B4, or EIF2B5." (PMID 33800130, 2021).
tumor (2 papers, 2022 to 2025). "This supports the previous finding that RGS2 decreases global mRNA translation and protein synthesis, cellular stress response, and tumor growth by binding EIF2B3 and disrupting the EIF2-EIF2B GTPase cycle." (PMID 36230542, 2022). "Given these links, EIF2B3 may contribute to the coordination between translational control and post-translational modifications such as glycosylation, thereby influencing tumor progression and immune microenvironment dynamics in STS." (PMID 40963867, 2025).
EIF2B3 also shares sentences with these, for which no sentence is quoted: Vanishing White Matter disease (2 papers); Cerebroretinal vasculopathy (1); dementia (1); hypopharyngeal cancer (1); metachromatic leukodystrophy (1); neurodegenerative disease (1).